KCNF1 (potassium voltage-gated channel modifier subfamily F member 1)
Description:
Accelerates inactivation but has relatively little effect on deactivation. Each modulatory subunit has its own specific properties of regulation, and can lead to extensive inhibitions, to large changes in kinetics, and/or to large shifts in the voltage dependencies of the inactivation process. The gating kinetics depends on the nature and stoichiometry of the associated regulatory sunbunit. Fails to produce a potassium current when expressed alone.
Synonyms: Kv5.1; kH1; IK8; KCNF
Tractability: Small molecule: an approved drug acts on it; it belongs to a druggable protein family. Antibody: its Gene Ontology location is reachable by antibodies, with high confidence; UniProt places it where antibodies can reach, with medium confidence; UniProt predicts a signal peptide or a membrane-spanning region.
Gene: Protein-coding gene on chromosome 2 (10,911,096 to 10,914,225, forward strand). Ensembl gene ENSG00000162975.
Subcellular location: Cell membrane
Subcellular location (Human Protein Atlas): Golgi apparatus; Nucleoplasm; Primary cilium transition zone; Vesicles
Pathways (Reactome):
Neuronal System: Voltage gated Potassium channels
Gene Ontology:
Molecular function: protein binding; potassium channel regulator activity; monoatomic ion channel activity; voltage-gated potassium channel activity
Biological process: action potential; potassium ion transmembrane transport; potassium ion transport; monoatomic ion transport; non-motile cilium assembly; protein homooligomerization; transmembrane transport
Cellular component: membrane; plasma membrane; voltage-gated potassium channel complex; ciliary base
Genetic constraint (gnomAD): Loss-of-function variants: 9 observed, 27.09 expected, observed/expected ratio (o/e) 0.33, 90% interval 0.2 to 0.58. The upper end of that interval is the gene's LOEUF score, 0.58, which puts it in group 2 of 6, group 1 being the genes least tolerant of losing a copy. Missense variants: 422 observed, 667.91 expected, observed/expected ratio (o/e) 0.63, 90% interval 0.58 to 0.69. Synonymous variants: 312 observed, 293.87 expected, observed/expected ratio (o/e) 1.06, 90% interval 0.97 to 1.17.
Homologues: Orthologues: chimpanzee KCNF1 (100% identical), mouse Kcnf1 (96% identical), rat Kcnf1 (96% identical), pig KCNF1 (96% identical), rabbit KCNF1 (94% identical), dog KCNF1 (91% identical), guinea pig KCNF1 (86% identical), tropical clawed frog kcnf1 (74% identical), zebrafish kcnf1b (70% identical), zebrafish kcnf1a (64% identical). Paralogues in human: KCNB2 (39% identical), KCNS2 (32% identical), KCNS3 (32% identical), KCNV1 (31% identical), KCNC4 (31% identical), KCNC3 (30% identical), KCNC2 (30% identical), KCNV2 (30% identical), KCNC1 (30% identical), KCNS1 (30% identical), KCNG4 (29% identical), and 19 more.
Diseases named in the same sentence as KCNF1 in open-access papers:
KCNF1 is named in the same sentence as 22 diseases in open-access papers, as found by Europe PMC text mining. Sharing a sentence is not in itself a finding about the gene and the disease. The quoted sentences say what the papers report.
lung carcinoma (2 papers, 2023 to 2024). "Our studies implicate that KCNF1 functions in the nucleus through a permeation-independent mechanism and promotes lung cancer by enhancing ITGB4 signaling." (PMID 36385523, 2023). "To determine the role of KvS subfamilies in NSCLC, we explored the lung cancer datasets from The Cancer Genome Atlas (TCGA) to inquire expression levels of KCNF1 (Kv5.1), KCNG4 (Kv6.4), KCNV2 (Kv8.2), and KCNS1 (Kv9.1)." (PMID 36385523, 2023). "Our findings suggest that KCNF1 promotes lung cancer by enhancing ITGB4 signaling and implicate KCNF1 as a novel therapeutic target for lung cancer." (PMID 36385523, 2023). "To determine the biological function of KCNF1 in lung cancer, we first analyzed its expression in a non-transformed human lung epithelial cell line, Beas2B, and NSCLC cell lines, A549, H23, and H2122." (PMID 36385523, 2023). "Thus, having the ability to specifically target electrically silent KCNF1 in lung cancer could provide the long-awaited significant advantage of not affecting normal and physiologically expressed K+ channels, but more precisely targeting cancer cells." (PMID 36385523, 2023).
bipolar disorder (1 paper, 2015). A disorder of the brain that causes unusual shifts in mood, energy, activity levels and the ability to carry out day-to-day tasks. "We identified three rare deletions in KCNJ6, UNC13C, OTOL1 and 7 rare duplications in CNTNAP2/MIR548F3, CORO7/VASN, DTNB, EMID2, KCNF1, PDPR and SGTA/THOP1 that are present in children with bipolar disorder (and their parents)." (PMID 25887117, 2015).
cognitive decline (1 paper, 2025). "Therefore, the downregulation of VGF, NEUROD6, KCNF1, KCNE5, CRH, and RPH3A may contribute to the cognitive decline observed in elderly individuals with AD." (PMID 39834440, 2025).
epilepsy (1 paper, 2021). A brain disorder characterized by episodes of abnormally increased neuronal discharge resulting in transient episodes of sensory or motor neurological dysfunction, or psychic dysfunction. "Additionally, a number of VGKCs including KCNB2, KCNF1, KCNK6, KCNK9 and KCNJ5 are significantly upregulated in the NRXN1α+/- transcriptome, and gain of function of VGKCs has been identified in neurodevelopmental disorders including epilepsy." (PMID 34525970, 2021).
lung adenocarcinoma (1 paper, 2023). A carcinoma that arises from the lung and is characterized by the presence of malignant glandular epithelial cells. "Down-regulation of KCNF1 in lung adenocarcinoma cell lines, A549 and H23 cells, reduced cell proliferation, migration, and tumor progression in mouse xenografts." (PMID 36385523, 2023). "Expression of KCNF1 and KCNV2 was significantly increased, while expression of KCNS1 was decreased in lung adenocarcinoma." (PMID 36385523, 2023).
non-small cell lung carcinoma (1 paper, 2023). A group of at least three distinct histological types of lung cancer, including non-small cell squamous cell carcinoma, adenocarcinoma, and large cell carcinoma. "Here, we analyzed the expression of KvS subfamilies in human lung tumors and identified that potassium voltage-gated channel subfamily F member 1 (KCNF1) was up-regulated in non-small cell lung cancer (NSCLC)." (PMID 36385523, 2023).
cancer (4 papers, 2019 to 2023). A tumor composed of atypical neoplastic, often pleomorphic cells that invade other tissues. "Given its prior association with malignant tumor formation, we further validated ITGB4 as a potential KCNF1 target." (PMID 36385523, 2023). "Altogether, our results suggest that KCNF1 increases ITGB4 expression and signaling that disrupt cell adhesion and basement membrane integrity, thereby promoting cancer progression and metastasis." (PMID 36385523, 2023). "The function of KCNF1 in cell proliferation and cancer progression has not been previously explored." (PMID 36385523, 2023).
tumor (3 papers, 2023 to 2024). "Tumor samples had a significant increase in KCNF1 expression compared to the matched uninvolved lung from the same patient determined by immunoblotting." (PMID 36385523, 2023). "To define the mechanism by which KCNF1 elicits its tumor-promoting role, we performed microarray analysis using A549 cells transfected with either control or KCNF1 siRNAs." (PMID 36385523, 2023). "In the present study, we demonstrated that silencing of KCNF1 in NSCLC cells reduced cell proliferation and tumor burden in mouse xenografts." (PMID 36385523, 2023). "Silencing of KCNF1 in NSCLC cell lines reduced cell proliferation and tumor progression in mouse xenografts, re-established the integrity of the basement membrane, and enhanced cisplatin sensitivity." (PMID 36385523, 2023).
KCNF1 also shares sentences with these, for which no sentence is quoted: infection (3 papers); acute lymphoblastic leukemia (2); adenoma (1); breast carcinoma (1); cutaneous leishmaniasis (1); depression (1); fragile X syndrome (1); HCMV infection (1); leishmaniasis (1); lymphoma (1); neuroblastoma (1); neurodevelopmental disorder (1); renal cell carcinoma (1); typhoid fever (1).